USP19 (ubiquitin specific peptidase 19)
Description:
Deubiquitinating enzyme that regulates the degradation of various proteins by removing ubiquitin moieties, thereby preventing their proteasomal degradation. Stabilizes RNF123, which promotes CDKN1B degradation and contributes to cell proliferation (By similarity). Decreases the levels of ubiquitinated proteins during skeletal muscle formation and acts to repress myogenesis. Modulates transcription of major myofibrillar proteins. Also involved in turnover of endoplasmic-reticulum-associated degradation (ERAD) substrates. Mechanistically, deubiquitinates and thereby stabilizes several E3 ligases involved in the ERAD pathway including SYVN1 or MARCHF6. Regulates the stability of other E3 ligases including BIRC2/c-IAP1 and BIRC3/c-IAP2 by preventing their ubiquitination. Required for cells to mount an appropriate response to hypoxia by rescuing HIF1A from degradation in a non-catalytic manner and by mediating the deubiquitination of FUNDC1. Attenuates mitochondrial damage and ferroptosis by targeting and stabilizing NADPH oxidase 4/NOX4. Negatively regulates TNF- and IL-1beta-triggered NF-kappa-B activation by hydrolyzing 'Lys-27'- and 'Lys-63'-linked polyubiquitin chains from MAP3K7. Modulates also the protein level and aggregation of polyQ-expanded huntingtin/HTT through HSP90AA1.
Synonyms: KIAA0891; ZMYND9
Tractability: Small molecule: a high-quality ligand is known. Antibody: UniProt predicts a signal peptide or a membrane-spanning region. PROTAC: ubiquitination databases record sites on it; its protein half-life has been measured; a small molecule that binds it is known.
Target class: Enzyme; Hydrolase
Gene: Protein-coding gene on chromosome 3 (49,108,046 to 49,120,938, reverse strand). Ensembl gene ENSG00000172046.
Subcellular location: Endoplasmic reticulum membrane
Pathways (Reactome):
Metabolism of proteins: Ub-specific processing proteases
Gene Ontology:
Molecular function: cysteine-type deubiquitinase activity; Hsp90 protein binding; protein binding; cysteine-type peptidase activity
Biological process: ERAD pathway; protein deubiquitination; protein stabilization; regulation of cellular response to hypoxia; regulation of ERAD pathway; response to endoplasmic reticulum stress; negative regulation of skeletal muscle tissue development; positive regulation of cell cycle process; regulation of protein stability
Cellular component: cytosol; endoplasmic reticulum membrane
Genetic constraint (gnomAD): Loss-of-function variants: 32 observed, 144.96 expected, observed/expected ratio (o/e) 0.22, 90% interval 0.17 to 0.3. The upper end of that interval is the gene's LOEUF score, 0.3, which puts it in group 1 of 6, group 1 being the genes least tolerant of losing a copy. Missense variants: 1,411 observed, 1,795.4 expected, observed/expected ratio (o/e) 0.79, 90% interval 0.75 to 0.82. Synonymous variants: 654 observed, 702.78 expected, observed/expected ratio (o/e) 0.93, 90% interval 0.87 to 0.99.
Homologues: Orthologues: chimpanzee USP19 (97% identical), macaque USP19 (92% identical), dog USP19 (89% identical), rabbit USP19 (88% identical), pig USP19 (88% identical), guinea pig USP19 (85% identical), mouse Usp19 (85% identical), rat Usp19 (83% identical), tropical clawed frog usp19 (59% identical), zebrafish usp19 (56% identical). Paralogues in human: USP4 (19% identical), USP15 (18% identical), USP32 (18% identical), USP11 (18% identical), USP31 (17% identical), USP43 (16% identical), USP6 (15% identical), USP9X (15% identical), USP9Y (14% identical), USP8 (14% identical), USP24 (14% identical), USP2 (13% identical), and 59 more.
Diseases named in the same sentence as USP19 in open-access papers:
USP19 is named in the same sentence as 55 diseases in open-access papers, as found by Europe PMC text mining. Sharing a sentence is not in itself a finding about the gene and the disease. The quoted sentences say what the papers report.
breast cancer (9 papers, 2011 to 2025). A primary or metastatic malignant neoplasm involving the breast. "We next investigated whether USP19-CY expression can be linked to the prognosis of breast cancer patients." (PMID 36646950, 2023). "Indeed, a previous study in which high expression of USP19 was found to be associated with a significantly lower frequency of distant relapse-free survival in early breast cancer patients." (PMID 36646950, 2023). "This offers a possibility that USP19-CY expression might be linked to poor prognosis in breast cancer patients, but further survival analysis of patients with differential USP19-CY needs to be performed to validate this hypothesis." (PMID 36646950, 2023). "Finally, a retrospective study conducted on human breast tumor samples indicated that high USP19 protein levels are associated with a high-risk for metastatic relapse in patients diagnosed with early breast cancer." (PMID 33714979, 2021). "In addition, we showed that USP19 overexpression is associated with distant relapse in patients diagnosed with early breast cancer." (PMID 33714979, 2021). "Importantly, consistent with the pro-invasive/EMT effects of the USP19-CY variant, we revealed that USP19-CY is more highly expressed in breast cancer tissues than in phenotypically normal adjacent tissues, and the higher expression level is related to more advanced cancer stages." (PMID 36646950, 2023). "Overexpression of USP19 increases the migratory and invasive abilities of breast cancer (MCF7) cells." (PMID 36969062, 2023). "Knockdown of USP19 reduces tumour aggressiveness, suggesting that USP19 plays a key role in the migration of breast cancer cells." (PMID 36969062, 2023). "We observed that the USP19-CY levels were higher in breast cancer tissues than in normal adjacent tissues." (PMID 36646950, 2023). "In another study, overexpression of USP19-ER was found to increase breast cancer cell migration and invasion, which was dependent on its catalytic activity." (PMID 36646950, 2023). "In order to study the putative mechanism of action responsible for USP19 migration and invasion regulation, we performed an in silico analysis on breast cancer mRNA expression using publicly available datasets." (PMID 33714979, 2021). "Altogether these results provide evidence indicating that USP19 has great potential as a therapeutic target for drug development in breast cancer treatment." (PMID 33714979, 2021). "Collectively, our data suggest that USP19 plays a crucial role in breast cancer cell dissemination, and we provide novel evidence that it can be a prognostic marker and attractive candidate for the development of new therapeutic strategies." (PMID 33714979, 2021). "We then analyzed the effect of USP19 overexpression in a poorly migratory and non-invasive breast cancer cell line (MCF7)." (PMID 33714979, 2021). "Altogether these findings indicate that USP19 represents a new predictor of distant metastasis formation in early breast cancer patients." (PMID 33714979, 2021). "We identified the deubiquitinase USP19 and demonstrated that its silencing reduces the migratory and invasive potential of highly invasive breast cancer cell lines." (PMID 33714979, 2021). "It was the important mechanisms by which USP19 inhibited breast cancer carcinogenesis." (PMID 37700495, 2023). "Importantly, we observed USP19-CY promoted the extravasation of MDA-MB-231 breast cancer cells in a zebrafish xenograft model." (PMID 36646950, 2023). "Furthermore, USP19-CY expression is correlated with poor prognosis and is higher in breast cancer tissues than in adjacent normal tissues." (PMID 36646950, 2023). "It will be interesting to explore the potential use of USP19-CY as a prognostic biomarker in breast cancer treatment and its potential use as a molecular target either by redirecting splicing to yield USP19-ER or inhibiting its deubiquitinating activity with selective small molecules." (PMID 36646950, 2023).
breast cancer (continued). "Notably, the splicing modulator herboxidiene inhibits USP19-CY, increases USP19-ER expression and suppresses breast cancer cell migration." (PMID 36646950, 2023). "Targeting USP19 splicing or its deubiquitinating activity may have potential therapeutic effects on breast cancer." (PMID 36646950, 2023). "Collectively, our results suggest that USP19-CY is highly expressed in breast cancer tissues." (PMID 36646950, 2023). "Finally, we showed that USP19 overexpression is a surrogate prognostic marker of distant relapse in patients with early breast cancer." (PMID 33714979, 2021). "Moreover, we performed an in silico analysis on breast cancer mRNA expression publicly available datasets, which revealed that high USP19 expression levels correlate with the activation of the Wnt pathway." (PMID 33714979, 2021). "Altogether, these findings demonstrate that USP19 might represent a novel therapeutic target in breast cancer." (PMID 33714979, 2021). "Here we report the identification of USP19 as a positive regulator of migration in breast cancer." (PMID 33714979, 2021). "Finally, we analyzed USP19 protein expression in a cohort study of early breast cancer patients with long-term follow-up." (PMID 33714979, 2021). "We next asked whether the regulatory role of USP19 in breast normal epithelial cell growth applied in human breast cancer using the MCF7 and MDA-MB-231 carcinoma cell lines." (PMID 21264218, 2011). "Thus it appears that the ability of USP19 to regulate cell growth and p27Kip1 levels is lost in these breast carcinoma cells, similar to the situation noticed above in the LNCaP cells." (PMID 21264218, 2011). "Moreover, consistent with these findings, USP19-CY is highly expressed in breast cancer tissues." (PMID 36646950, 2023). "Similarly, our group analyzed USP19 clinical significance in breast cancer." (PMID 35646888, 2022). "Finally, we conducted a retrospective analysis on early breast cancer patients which revealed that USP19 expression levels correlated with poor outcome and reduced distant metastasis free survival, hence serving as a prognostic factor in early breast cancer patients." (PMID 35646888, 2022). "Based on our data showing that the control of cell migration in breast cancer cells is mainly exerted by the transmembrane USP19 isoform, it is plausible to assume that this difference could contribute to explain the divergent role that USP19 plays in these two different cellular contexts." (PMID 33714979, 2021). "We discovered that there are three genes (DHX30, USP19, and RBM15B), which are highly positively correlated with BAP1 in both black and white breast cancer patients." (PMID 30716094, 2019). "DHX30 has the highest positive correlation with BAP1 in black-alive and white-dead categories, while USP19 has the maximum positive correlation with BAP1 in black-dead and white-alive breast cancer categories." (PMID 30716094, 2019). "In breast cancer (BC) models, the cytoplasmic isoform USP19 stabilizes both the TβRI and TβRII to enhance TGF-β-induced EMT and cell migration, whereas the endoplasmic reticulum-localized isoform USP19 inhibits EMT by reducing TβRI surface expression." (PMID 41208892, 2025). "Furthermore, more advanced breast cancer tissue stages, i.e., stage IIIA and IIIB demonstrated higher expression of USP19-CY compared than breast cancer tissue stages IIA and IIB." (PMID 36646950, 2023). "Moreover, USP19-ER inhibits TGF-β-induced epithelial–mesenchymal transition (EMT), whereas USP19-CY enhances EMT, as well as the migration and extravasation of breast cancer cells." (PMID 36646950, 2023). "Consequently, our results indicate that the functional interaction between USP19 and LRP6 is key for the regulatory effect that USP19 exerts on the modulation of breast cancer cell migration and invasion." (PMID 33714979, 2021).
breast cancer (continued). "Our results also indicated that USP19 does not affect breast cancer cells proliferation in two dimensions, in concordance with Lu and collaborators, but significantly modulates proliferation and invasion if cells are grown embedded in extracellular matrix proteins and basement membrane proteins." (PMID 35646888, 2022). "A previous study on the expression of BAP1 tumor suppressor gene in 1222 patients with TCGA breast cancer data reported that the expression of BAP1, which enhances BRCA1-mediated suppression of cell proliferation through BRCA1 stabilization, is highly correlated with USP19 expression." (PMID 34439131, 2021). "Interestingly, although USP19 could regulate cell growth in MCF10A breast epithelial cells, this regulation was lost in breast cancer MCF7 and MDA-MB-231 cells." (PMID 21264218, 2011).
cardiac hypertrophy (4 papers, 2020 to 2025). "We generated USP19‐knockout mice and isolated neonatal rat cardiomyocytes (NRCMs) that overexpressed or were deficient in USP19 to investigate the effect of USP19 on transverse aortic constriction (TAC) or phenylephrine (PE)‐mediated cardiac hypertrophy." (PMID 32798288, 2020). "An important role for USP19 in the innate immune response has now been reported, with USP19 blunting pathological cardiac hypertrophy by inhibiting the inflammatory response." (PMID 33628391, 2021). "Mechanistically, the USP19‐elicited cardiac hypertrophy improvement was attributed to the abrogation of the transforming growth factor beta‐activated kinase 1 (TAK1)‐p38/JNK1/2 transduction." (PMID 32798288, 2020). "The present study provides in vivo and in vitro data to reveal the role of USP19 in preventing pathological cardiac hypertrophy." (PMID 32798288, 2020). "The study provides in vivo and in vitro evidence that USP19 functions as a negative regulator of pathological cardiac hypertrophy by inhibiting the TAK1‐p38/JNK1/2 signalling pathway in the hypertrophic hearts and cardiomyocytes." (PMID 32798288, 2020). "The extent of TAC‐induced cardiac hypertrophy, fibrosis, dysfunction and inflammation in USP19‐knockout mice was exacerbated." (PMID 32798288, 2020). "The present study did ascertain through the data that USP19 positively prevented the pressure overload and neurohormonal factor‐induced cardiac hypertrophy." (PMID 32798288, 2020). "In the present study, a significantly increase in USP19 expression during the development of pathological cardiac hypertrophy increased the possibility that USP19 may play a critical role in this processes." (PMID 32798288, 2020). "The therapeutic pharmacological activation or genetic elevation of USP19 levels might be a reasonable strategy for cardiac hypertrophy and heart failure." (PMID 32798288, 2020). "By subjecting USP19 knockout mice to angiotensin II (AngII) stimuli or cardiac pressure overload, which was performed by transverse aortic constriction (TAC), the USP19 deficiency exacerbated the cardiac hypertrophy, fibrosis, dysfunction and inflammation." (PMID 32798288, 2020). "Given the similarity between skeletal muscle cells and cardiomyocytes, and that USP19 is expressed in rodent hearts in considerable levels, it can be speculated that USP19 may protect against cardiac hypertrophy." (PMID 32798288, 2020). "Furthermore, the silencing USP19 inhibits denervation‐ or glucocorticoid‐induced muscle atrophy by suppressing protein degradation, with a notably decreased expression of the ubiquitin ligases MuRF1 and MAFbx/atrogin‐1,12 which are correlated to the cardiac hypertrophy blockade." (PMID 32798288, 2020). "In conclusion, the present study revealed that USP19 and the downstream of TAK1‐p38/JNK1/2 signalling pathway might be a potential target to attenuate pathological cardiac hypertrophy." (PMID 32798288, 2020). "Thus, targeting USP19 and its interaction with TAK1 may represent promising strategies for reversing cardiac hypertrophy and dysfunction." (PMID 32798288, 2020). "Considering that aroused inflammatory response was one of the phenotypes of cardiac hypertrophy, we subsequently detected total and phosphorylated IKKα, IκBα and p65 in NF‐κB axis, and transcriptional levels of pro‐inflammatory cytokines in WT and USP19‐KO mice with or without TAC intervention." (PMID 32798288, 2020).
colorectal cancer (4 papers, 2022 to 2025). A primary or metastatic malignant neoplasm that affects the colon or rectum. "Besides, a recent study reported that upregulation of USP19 contributed to tumourigenicity of colorectal cancer cells by stabilizing Survivin protein." (PMID 38106991, 2023). "Finally, the authors showed that the USP19-ME1 signaling axis is dysregulated in human colorectal cancer samples, and that USP19 is upregulated during colorectal carcinogenesis pathogenesis and spontaneous tumor development." (PMID 35646888, 2022). "USP19 antagonizes RNF1-mediated degradation of ME1 through deubiquitination, thereby promoting lipid metabolism and NADPH production while suppressing ROS, consequently triggering the progression of colorectal cancer." (PMID 39944823, 2025).
ovarian carcinoma (4 papers, 2020 to 2023). A malignant neoplasm originating from the surface ovarian epithelium. "There are more studies on identifying important DUBs such as USP8 and USP19 in ovarian cancers." (PMID 37107644, 2023). "On contrast, diminished USP19 expression in ovarian cancer correlates with an adverse prognosis." (PMID 38106991, 2023). "As for the ovarian cancers, this is the first study to report that USP19 is a putative prognostic marker, demonstrating that its low expression is significantly related to cancer recurrence and worse prognoses in patients with HGSC receiving conventional therapy." (PMID 34439131, 2021). "Therefore, we suggest USP19 and RPL23 as candidate biomarkers for predicting the survival of patients with ovarian cancer." (PMID 34439131, 2021).
breast tumor (3 papers, 2011 to 2022). "We demonstrated that USP19 positively regulates breast tumor cells migration and invasion in vitro, and that genetic silencing reduces cells motility, whereas its overexpression increases migratory and invasive capabilities—dependent on USP19’s catalytic activity and ER localization." (PMID 35646888, 2022). "It appears from expression profiling studies that USP19 mRNA transcripts do not increase in breast tumors (Hallett, M and Park M, unpublished data) nor in prostate cancers compared to their normal adjacent tissues." (PMID 21264218, 2011).
Ewing sarcoma (3 papers, 2019 to 2022). A small round cell tumor that lacks morphologic, immunohistochemical, and electron microscopic evidence of neuroectodermal differentiation. "This indicates that a USP19 mediated degradation of EWS-FLI1 supports the loss of Ewing sarcoma cell growth any time between 4 and 8 days where again expression levels of some, but not all of the tested target genes were modulated." (PMID 30700749, 2019). "Inhibitors of USP7 and USP19 have been developed, and their effects on Ewing sarcoma remain to be determined." (PMID 34060252, 2021). "Most likely, USP19, and other DUBs, modulate fusion protein levels to maintain Ewing sarcoma cell viability." (PMID 30700749, 2019). "We depleted USP19 with three different siRNAs prior to immunoprecipitation of tagged ubiquitinated EWS-FLI1 expressed in A673 Ewing sarcoma cells." (PMID 30700749, 2019). "We observed selectively diminished cell growth, proliferation and colony formation in two Ewing sarcoma cell lines upon specific USP19 depletion." (PMID 30700749, 2019). "Two deubiquitinases, USP7 and USP19 had been reported as vulnerabilities in Ewing sarcoma." (PMID 34060252, 2021). "To validate that USP19 depletion could be relevant in Ewing sarcoma cells, we analyzed protein and mRNA expression of USP19 across six different Ewing sarcoma cell lines and three primary cell samples." (PMID 30700749, 2019). "Finally, we investigated the physiological consequences of USP19 depletion on Ewing sarcoma cell growth." (PMID 30700749, 2019). "Even though only few USP19 substrates have been identified so far without a common ontology, USP19 expression clearly seems to be oncogenic in the context of Ewing sarcoma as USP19 depletion did not influence cell viability of control cell lines of non-tumorigenic origin." (PMID 30700749, 2019).